CCL2 (C-C motif chemokine ligand 2)
Diseases named in the same sentence as CCL2 in open-access papers (continued):
Sharing a sentence is not in itself a finding about the gene and the disease.
tumor (continued). "By day 8 after tumor cell inoculation, blood levels of CCL2 and CD115hi cells were significantly higher than in sham-treated mice without tumors, indicating that these effects are tumor specific." (PMID 37013652, 2023). "Furthermore, CCL2 in tumors and CCR2 on tumor-infiltrating monocytes were increased with combination anti-PD-1/CTLA-4 treatment." (PMID 37449205, 2023). "Conversely, levels of apelin, CCL2, progranulin, interleukin-6, chemerin, retinol binding protein 4 (RBP4), resistin, and plasminogen activator inhibitor-1 (PAI-1) expression were lower in tumor tissue than in adjacent normal tissue." (PMID 36917086, 2023). "Moreover, CAF, which is a significant source of CCL2, can also activate the STAT3 signaling pathway to increase MDSCs recruitment and promote tumor progression." (PMID 37007004, 2023). "To demonstrate this idea, we applied the tumor immune dysfunction and exclusion (TIDE) algorithm to evaluate whether CCL2 can predict the response of GBM patients to ICB therapy." (PMID 38057698, 2023). "Optimizing the CAR to express the appropriate chemokine receptor to the tumor could improve trafficking and anti-tumor effect, as shown in a study of GD2-CAR T cells expressing CCR2b in CCL2-secreting tumors." (PMID 37754534, 2023). "TAM recruitment by CCL2 and CCR2 is critical to tumour invasion and metastasis." (PMID 37965573, 2023). "The ELISA of serum collected at the time of sacrifice revealed an increase in CCL2 in all mice which received i.t. anti-CCL2 compared to isotype-control-treated mice independent of the tumor-derived TNC status." (PMID 37176074, 2023). "These infiltrated immune cells and solid tumor cells release tumor-progressing cytokines (IL-6, TNF-α, TGF-β), chemokines (CCL2, CCL5, CCL18, CXCL8, CXCL12), and growth factors (EGF, PGF, IGF-1, IGF-2, PDGF) that promote tumor microenvironment immunosuppressive." (PMID 37371075, 2023). "Intranasal delivery of CCL2 to BALB/c mice markedly enhanced the seeding and outgrowth of 67NR cells in the lung and increased the recruitment of CD4+ T cells and CD8+ central memory T cells into the lungs of tumor-bearing mice." (PMID 37208442, 2023). "Similarly, TANs promote TAMs and T–regulatory cell recruitment in hepatocellular carcinoma via secreting CCL2 and CCL17, leading to tumor growth and drug resistance." (PMID 36845095, 2023). "The expression of CCL2 was negatively related to the overall stage, but not related to tumor grade, ER, PR, or HER2 status in patients with BC." (PMID 36794651, 2023). "Activating the NF-κB signaling pathway could also promote CCL2 expression, contributing to MDSC accumulation in the tumor microenvironment." (PMID 37865804, 2023). "For instance, in a murine hepatocarcinoma model, it has been shown that activated MCs can promote the infiltration of myeloid-derived suppressor cells (MDSCs) through the CCL2/CCR2 axis and their production of IL-17, which in turn recruits Tregs at the tumor site." (PMID 37376140, 2023). "Peripheral blood and tumor tissue were analyzed mechanistically by flow cytometry using antibodies against CD115/CSF1R and F4/80 and by ELISA for chemokine (C–C motif) ligand 2 (CCL2) levels." (PMID 37013652, 2023). "It is possible that the TNC/CCL2 interplay influences end stage tumor biology rather than early stage." (PMID 37176074, 2023). "By releasing chemoattractant factors, including monocyte chemoattractant protein-1 (CCL2/MCP-1) or even stromal cell-derived factor 1 (CXCL12/SDF-1), tumor cells actively recruit circulating monocytes and facilitate their migration to the tumor area." (PMID 36986856, 2023). "To identify candidate stroma-derived factors that might influence desmoid tumor cell proliferation, we treated mutant-only cultures with recombinant IGFBP3, PTX3, CCL2, CXCL12, and CHI3L1 in serum-free conditions." (PMID 37377751, 2023).
tumor (continued). "In mice injected with the TRAMP-C2/Luc-eGFP cells, only co-injection of WT MSCs (T+WT) showed significant tumor growth, compared with those with CCL2 KO MSCs (T+#1 and T+#2) or no MSCs (Tumor only)." (PMID 36672395, 2023). "In our study, CCL2 at concentrations secreted by tumor cells did not affect murine mBMM survival or TNFα secretion and an analysis of CCL2s impact on these readouts did not change in the context of different matrix substrates." (PMID 37176074, 2023). "As a result, STING agonist administration enhances the expression of IFN-β and other proinflammatory cytokines (e.g., IL-6 and TNF-α) or chemokines (e.g., CCL2/3/4/5 and CXCL9/10), the maturation and functions of DCs, and the expansion of tumor-infiltrating CD8+ T cells." (PMID 38008741, 2023). "In contrast to the significant impact of tumor-derived TNC on tumor growth, the growth was not significantly impacted by anti-CCL2 treatment in this model." (PMID 37176074, 2023). "After anti-HER2 treatment, in tumours exhibiting HER2 amplification, there would be a downregulation in the release of cytokines, including CCL2, CCL21, VEGF, and CXCL1, which leads to an amelioration of the immunosuppressive factors within the tumour microenvironment." (PMID 37720943, 2023). "In contrast to the 4T1 and CT26 models, Ccl2 mRNA expression in CT26-TRAIL-R-KO tumor tissues was not affected by smTRAIL treatment, whereas Ccl2 mRNA expression in 4T1-TRAIL-R-KO tumor tissues was significantly inhibited in the smTRAIL-treated groups." (PMID 37605148, 2023). "To determine whether EZH2 suppression facilitated anti-tumor NK cell immunity through CCL2 induction, we also treated mice transplanted with shEzh2 KPC1 PDAC tumors with vehicle, T/P, and/ or a mAb targeting CCL2 (2H5)." (PMID 37142692, 2023). "In the TME, tumor cells recruit and reeducate macrophages to adopt a special phenotype by secreting vascular endothelial growth factor (VEGF), platelet-derived growth factor (PDGF), TGF-β, CCL2, or M-CSF." (PMID 36816959, 2023). "Therefore, CCL2 and CCL7 are the main CC chemokines secreted by the 231 TFM tumor spheroids that induce monocyte recruitment from the vasculature." (PMID 38076998, 2023). "Tumor cells attract these cells to the microenvironment and alter their functions and phenotypes by secreting chemoattractants, such as MIC-1, MCP-1, GM-CSF, S100A8/9 and CCL2, to create an immunosuppressive milieu that aids in evading anti-tumor immunity." (PMID 37234776, 2023). "CCL2 has pro-tumor effects and CCL2 affects vascular endothelial cells through the JAK2-STAT5 and P38 mitogen-activated protein kinase pathways, regulating tumor vascularization and tumor metastasis." (PMID 36959811, 2023). "CCL2 may be derived directly from CT26 and MC38 tumor cells, as observed in in vitro cultures, although this was not seen for CT26 cells by others, or induced in vivo under hypoxic conditions in tumor cells or other cells of the tumor microenvironment." (PMID 37013652, 2023). "CCL2 did not directly affect tumor cell proliferation because tumor cells isolated from neu+, Ccl2-/- neu+, and Ccr2-/- neu+ mice grew at similar rates in vitro." (PMID 37208442, 2023). "Therefore, to better understand tumor regression and the influence of JOL2888 on TAMs, we examined the levels of these three key TAMs (CD68, CCL2, and iNOS)." (PMID 37941832, 2023). "Furthermore, TAMs can enhance invasion, migration, and the circulating tumor cell-mediated metastasis of colorectal cancer by regulating the JAK2/STAT3/miR-506-3p/FoxQ1 axis, which leads to CCL2 production." (PMID 37509382, 2023). "The CCL2/CCR2 axis has been shown to not only regulate the infiltration and activation of monocytes, T lymphocytes, and NK cells, but to directly mediate angiogenesis, promote tumor invasion, and metastasis." (PMID 36838599, 2023).
tumor (continued). "CCL2 recruits circulating macrophages in the TME to form a crown-like structure, which leads to the release of a series of inflammatory mediators that promote tumor angiogenesis and immunosuppression." (PMID 36765683, 2023). "According to the IHC results, CCL2 expression was observed in both CD68+ TAMs and tumor cells." (PMID 37208442, 2023). "Using multiplex immunoassays, we examined type I IFN (IFN-α, IFN-β), type II IFN (IFN-γ), proinflammatory cytokine (GM-CSF, IL-6, IL-12p70), and proinflammatory chemokine (CXCL10 [IP-10], CCL2 [MCP-1], CCL3 [MIP-1α], CCL5 [RANTES]) signaling in the tumor microenvironment (TME)." (PMID 36810257, 2023). "We therefore chose GM-CSF-stimulated mBMMs for all further assays to model the impact of tumor-derived CCL2 on macrophage behavior in the presence or absence of TNC or a more complex tumor-derived ECM." (PMID 37176074, 2023). "MCP-1 (12kD protein) belongs to the family of the C–C motif chemokine, which binds with the CCR2 receptor, which is a GPCR, where it recruits monocytes that later secrete CCL2 chemokine, resulting in tumor proliferation and invasion." (PMID 37174125, 2023). "Our results showed an increase in the infiltration of macrophages to tumour sites in CCL2 overexpressing mice; however, our studies did not delineate the phenotype or functions of these macrophages." (PMID 37108548, 2023). "Moreover, upon antigenic activation in vitro, PB CAR-T cells released lower levels of IFN-γ, IL-6, IL-10, TNF-α, CCL2, CXCL10, and GM-CSF than Lenti CAR-T cells, but demonstrated a robust release of IL-9, indicative of a distinct anti-tumor response pathway." (PMID 37228617, 2023). "Similarly, CCL2 and CCL5 released by CSCs contribute to both macrophage infiltration and skew them towards the tumor-supporting M2 subtype." (PMID 38035101, 2023). "In addition, celecoxib has been found to reduce microglia and macrophages by inhibiting the expression of CCL2 and CXCL10 and28, in addition to its direct antitumor effects through the promotion of tumor cell apoptosis and regulation of cell cycle." (PMID 37598273, 2023). "The addition of neutralizing anti-CCL2 Ab (R&D Systems) to WT tumor cells or exogenous CCL2 to Ccl2-/- tumor cells did not affect their proliferation." (PMID 37208442, 2023). "Positive CCL2 staining of stromal cells, but not tumor cells, had a significant correlation with relapse-free survival." (PMID 37208442, 2023). "Tumor-free survival was unchanged in Ccl2-/- neu+ mice compared to neu+ mice, but the rate of tumor growth, measured as total tumor burden or as the rate of growth of the single largest tumor mass, was slower in the absence of CCL2." (PMID 37208442, 2023). "If these receptors on tumor cells are similarly inhibited by RANKL, then inhibition of RANKL by denosumab would increase their expression and enhance pro-tumoral signaling by the osteoid cell-derived chemokines CCL2, CCL5, CXCL16, and CX3CL1." (PMID 37025604, 2023). "BC tumor-derived SEVs can induce an M1 proinflammatory response in macrophages through the activation of NFκB, which stimulates the production of inflammatory cytokines including GCSF, IL-6, IL-8, IL-1β, CCL2, and TNF-α." (PMID 37108371, 2023). "CCL2 and CCL5, in addition to acting as chemokines, are known to regulate cancer progression by regulating various signaling pathways of cancer cells in the tumor microenvironment." (PMID 36766725, 2023). "Indeed, inflammatory CC (such as CCL2, CCL3, and CCL5) chemokines join the CCR2+ monocytes that differentiate into TAMs at the tumor site." (PMID 36980182, 2023). "As for chemokines, such as CCL2, CCL3 and CXCL1, their expressions in GISTs are relatively high and CCL2 induces the infiltration of macrophages into tumor tissues and promotes tumor growth." (PMID 37072770, 2023). "MDSCs are increased in the TME following RT in mouse models, the accumulation of which is through CCL2 – CCR2 signaling and CCL2 may be derived from tumor cells." (PMID 37221584, 2023).
tumor (continued). "However, monocytes that differentiate into macrophages in the tumor microenvironment are mainly recruited by CCR2 ligands, such as CCL2/MCP-1." (PMID 37686093, 2023). "Though studies have reported that CCL2 is an important factor in inducing tumor progression, clinical trials targeting CCL2 did not yield promising results." (PMID 36900416, 2023). "Chemokines such as CCL2, CXCL5, and CXCL8 recruit immature myeloid cells to the tumor stroma." (PMID 37415162, 2023). "Tumor-derived UBR5 promotes TAM recruitment and activation via key cytokines like CCL2 and CSF1." (PMID 37865750, 2023). "Conversely, platelet microparticles may direct macrophage activation, which can inhibit tumor growth through cytokines such as TNF-related apoptosis-inducing ligand (TRAIL), CCL2 (also known as monocyte chemoattractant protein 1 (MCP-1)) and IL-8." (PMID 36831623, 2023). "The production of CCL2 by tumor cells leads to the absence of embryonic KCs in tissue and promotes the infiltration of monocyte-derived KCs and immature monocytes (M0)." (PMID 37663266, 2023). "CCL2 and CCL5 can recruit monocytes to migrate toward tumor foci." (PMID 38057852, 2023). "Moreover, nonmutant fibroblasts have the potential to increase the proliferation of mutant desmoid tumor cells by secreting soluble factors that include PTX3, CCL2, and CXCL12." (PMID 37377751, 2023). "Except for CXCR6, all cytokines/cytokine receptors were shown to operate in the spine, with CX3CL1, CX3CR1, IL10, CCL2, CXCL12, and CXCR4 mediating bone marrow colonization, CXCL5 and TGFβ promoting tumor cell proliferation, and TGFβ additionally driving bone remodeling." (PMID 36835198, 2023). "We also observed that MDSC-secreted VEGFA and multiple chemokines CCL2, CXCL1, CXCL2, CXCL3, and CXCL8 could act on endothelial cells via VEGFA-KDR/FLT1 and CCL2/CXCLs-ACKR1 interactions, which were crucial for tumor angiogenesis." (PMID 37475874, 2023). "CCL2 is over-expressed in CRC, along with its main receptor CCR2 boosts the progression of cancer by promoting proliferation, survival, angiogenesis, migration, and invasion and contributes to tumor metastasis." (PMID 37325423, 2023). "Further investigation is required to address whether tumor cells exhibiting inflammatory TME exhibit distinct immune responses to WT and CCL2 MSCs." (PMID 36672395, 2023). "In addition, TNF-α, a central mediator of free radical-induced oxidative stress and inflammatory reactions, activates NF-κB, and this induces tumor cells to secrete various cytokines, such as VEGF, MCF-1/CCL-2, IL-8, and COX-2." (PMID 37434755, 2023). "Following intrarenal injection of CHLA-255-Fluc or NGP-Fluc cells in mice and subsequent resection of the primary tumor, mice were treated with control (PBS), anti-CCL2 antibody alone, etoposide alone, or with the combination therapy of etoposide plus anti-CCL2 antibody." (PMID 37964011, 2023). "The CCL2/CCR2 axis is also important for TAMs recruitment and therapies that target these proteins have shown to be effective in this sense and they also reduce tumor growth." (PMID 37284199, 2023). "However, once a tumor succeeds in growing and establishes an inflammatory TME, monocyte-derived macrophages recruited via the CCL2/CCR2 axis are rapidly reprogrammed and protect the growing tumor by NK cell inactivation." (PMID 36845555, 2023). "Although the presence of chemokines such as CCL2 may lead to SMAD3 phosphorylation, using a TGF-β1 receptor specific inhibitor, we confirmed that tumor-secreted TGF-β1 is solely responsible for the pSMAD3 response in TCM-treated cells." (PMID 37682817, 2023). "Since unstimulated stromal cells do not produce a significant amount of CCL2, it is likely that tumor stromal cells, including TAMs and fibroblasts, are activated by interacting with BC cells." (PMID 37208442, 2023).
tumor (continued). "Additionally, FAP regulates tumor growth and invasiveness by increasing angiogenesis and reducing the immune system's antitumor response mediated by the STAT3/CCL2 signaling pathway." (PMID 37316886, 2023). "Although the antibody inhibited the migration of MCF10CA1d cells in response to CCL2 in vitro, it did not significantly affect tumor growth, invasion, macrophage recruitment, or tumor angiogenesis." (PMID 37208442, 2023). "While the tumor cells release CCL2 to recruit monocytes and induce their differentiation and polarization to M2 macrophages, the latter release epidermal growth factor (EGF) that upregulates CCL2 expression in tumor cells." (PMID 37711747, 2023). "CCL2, CCR2, CD163, and CD4 were all widely expressed in both CNB and resected tumor samples." (PMID 37208442, 2023). "Besides, CAFs, major sources of chemokines, including CXCL12, CCL2 and CXCL1, can recruit MDSCs to tumor sites and promote their differentiation and activation." (PMID 37046312, 2023). "Additionally, TAM-derived IL-6 in turn elevated CCL2 and EIF4A3 expression in tumor cells by increasing the activation of the JAK2-STAT3 pathway." (PMID 36797769, 2023). "Additionally, tumor cells secrete various chemokines such as SDF-1, CCL2, CCL5, and adiponectin which mediate the homing of endothelial progenitor cells into tumor neovasculature." (PMID 36091174, 2022). "Therefore, targeting CCL2/CCR2 and CXCLs/CXCR2 can potentially regulate immune cell infiltration in the tumor microenvironment and improve the therapeutic effect of HCC." (PMID 36403057, 2022). "Therefore, CCL2 expression in the tumor microenvironment attracts CCR2-expressing KLRG+ NK cells, leading to enhanced tumor-homing efficiency of NK cells." (PMID 35677043, 2022). "Based on the significant association between the two chemokine axes and HCC, we hypothesized that targeted therapies against CCL2/CCR2 and CXCLs/CXCR2 can improve the anti-tumor effect of TACE." (PMID 36403057, 2022). "The CCL2/CCR2 axis is involved in the recruitment of monocytes and macrophages to tumor sites." (PMID 36403057, 2022). "We then examined whether PYK2 depletion affects CCL2 transcription in human TNBC cell lines, murine EO771 BC cells, and EO771‐derived tumor tissues by qPCR." (PMID 35092356, 2022). "CCL2 secreted by oncogene-induced senescent hepatocytes can recruit CCR2+ immature myeloid cells and then inhibit the antitumor function of NK cells, thereby promoting HCC tumor growth." (PMID 35281057, 2022). "Based on the existing evidence, we hypothesized that blocking the CCL2/CCR2 and CXCLs/CXCR2 axes would enhance the TACE-induced inhibition of tumor growth." (PMID 36403057, 2022). "In CRC, CAF-derived CCL2 upregulates FGFR4, which plays a role in tumor-matrix interactions and promotes EMT, which may constitute an essential factor in CRC resistance to 5-FU and oxaliplatin." (PMID 35740594, 2022). "In mice, Fbw7 also regulates the tumor microenvironment through a non-tumor-cell-autonomous manner involving the expression of the CCL2 chemokine." (PMID 35225231, 2022). "CCL2 expression was significantly elevated in HONE1-IR cells and recurrent NPC tumours." (PMID 35365161, 2022). "Notably, cytokines such as CCL2, CCL5, and CSF1 were found to be involved in the attraction of MDSCs to the tumor site." (PMID 36430577, 2022). "Many cytokines secreted by tumor cells can recruit macrophages to the TME, but some of them are exclusively produced by CSCs: CCL2, CCL3, CCL5, CXC motif chemokine ligand 12 (CXCL12), olfactomedin-like 3 (OLFML3), stromal-cell-derived factor-1b (Sdf1b), IL-6, IL-33, and CSF-1." (PMID 35740975, 2022).